BACE2 (beta-secretase 2)
Diseases named in the same sentence as BACE2 in open-access papers (continued):
Sharing a sentence is not in itself a finding about the gene and the disease.
glioma (continued). "In addition, the BACE2‐overexpression (BACE2‐LentiOV) and control (BACE2‐LentiNC) glioma cell lines were obtained by lentivirus transfection of the U87MG and U251 cells." (PMID 31856384, 2020). "In the in vitro experiments, TGFβ1 induced BACE2 expression in two glioma cell lines." (PMID 31856384, 2020). "In this study, we observed that BACE2 could enhance invasion and migration cells in gliomas." (PMID 31856384, 2020). "Moreover, there was a correlation between BACE2 and TGFβ1 expression in glioma patients." (PMID 31856384, 2020). "Additionally, univariate and multivariate analysis showed that BACE2 might be an independent prognostic element in glioma." (PMID 31856384, 2020). "Thus, based on these results, BACE2 can promote the mesenchymal transition in gliomas." (PMID 31856384, 2020). "This study reports TGFβ1 stimulates beta‐site APP‐cleaving enzyme 2 (BACE2) expression through Smad‐dependent signalling, which modulates TNF‐α‐induced NF‐κB activity through the PP1A/IKK pathway to promote tumorigenesis in glioma cells." (PMID 31856384, 2020). "Finally, the role of BACE2 in promoting the EMT and proliferation of glioma was demonstrated through functional studies with knockdown and overexpression of BACE2." (PMID 31856384, 2020). "Furthermore, TGFβ1 stimulates BACE2 expression through Smad‐dependent signalling, which modulates TNF‐α‐induced NF‐κB activity through the PP1A/IKK pathway to promote tumorigenesis in glioma cells." (PMID 31856384, 2020). "Through western blot analysis, we observed that knocking down BACE2 suppressed EMT stimulated by TGFβ1 (10 ng·mL−1) in both U87MG and U251 cells, which indicated that BACE2 may be stimulated by TGFβ1 in glioma cells." (PMID 31856384, 2020).
diabetes (7 papers, 2013 to 2025). "Chromosome 21 also encodes other proteins, such as BACE2, RCAN1 and DYRK1A, known to be associated with diabetes mellitus phenotypes and potentially contribute to the increased risk of diabetes mellitus." (PMID 38474215, 2024). "The BACE2-selective inhibitors claimed specifically as potential anti-diabetes compounds are, as far as we can determine, the only public database instantiation of these activity mappings." (PMID 26464438, 2016). "Unsurprisingly, Roche patents specifying BACE2 inhibitors for diabetes first appeared in 2010 and have produced the strong upward spike as this enzyme transitions from cross-screening to a primary target." (PMID 24204758, 2013). "Previously, BACE2 has more been reported as the sheddase for pigment cell‐specific melanocyte protein or Tmem27 in β cell, therefore discussed as a potential drug target for melanoma metastasis or diabetes treatment." (PMID 40884245, 2025). "However, this situation changed abruptly in 2011 when BACE2 was declared as potential drug target for diabetes in a paper with Roche co-authors." (PMID 24204758, 2013). "BACE2 cleaves TMEM27 and thereby controls insulin homeostasis and pancreatic β cell mass and is discussed as a potential drug target for diabetes treatment." (PMID 38888964, 2024).
Down syndrome (7 papers, 2012 to 2024). "For example, the BACE2 haplotype associates with AD, while SNPs in BACE2 (e.g., rs2252576, rs2837990, and rs7281733) predispose to early onset of AD in Down syndrome." (PMID 32566665, 2020). "For example, BACE2 haplotype associates with AD, while SNPs in BACE2 (e.g., rs2252576, rs2837990, rs7281733) predispose to early onset of AD in patients with Down syndrome." (PMID 32160867, 2020). "The BACE2 gene is located on chromosome 21q22, and the accumulation of Aβ along with increased levels of BACE2 has been detected in patients with Down's syndrome." (PMID 22911757, 2012).
melanoma (7 papers, 2020 to 2025). A malignant, usually aggressive tumor composed of atypical, neoplastic melanocytes. "We observed that, in IGR37 metastatic melanoma cells, the inhibition of BACE2 (3I), which decreases amyloid maturation and secretion, decreases also YAP nuclear localization." (PMID 38199984, 2024). "BACE2 inhibition decreases the ability of melanoma spheroids to invade the surrounding Matrigel, and this effect is reverted by embedding rPMEL amyloid fibrils into the Matrigel." (PMID 38199984, 2024). "KPNA2, DTL, BACE2 and DTYMK cfRNA demonstrated high diagnostic accuracy between melanoma patients’ and healthy donors’ plasma (AUC > 86%, p < .0001)." (PMID 36320118, 2022). "Further, we demonstrated that BACE2 activity is required not only to produce amyloid fibrils but it also affects melanoma cells sensitivity to chemotherapy." (PMID 33926496, 2021). "Indeed, as observed in melanoma cells, both pharmacological inhibition and genetic knockdown of BACE2 reduce the level of amyloid aggregates in BXPC3." (PMID 38199984, 2024). "More recently, our and other research groups have addressed the involvement of BACE2 in cancer establishment and progression, in particular in melanoma and pancreatic cancer, where the processing of amyloidogenic proteins has been shown to increase cancer growth and metastasis formation." (PMID 38199984, 2024). "We also analysed cfRNA copies of KPNA2, DTL, BACE2 and DTYMK across different mutational genotypes of melanoma tissue (N = 33 BRAF/NRAS wild‐type, of those N = 4 positive for TERTprom; N = 41 BRAFV600 mutant and N = 25 NRASQ61 mutant melanomas)." (PMID 36320118, 2022). "Next, plasma cfRNA samples from melanoma patients (N = 18) versus control plasma of healthy donors (N = 18) were used to determine gene expression levels of six gene candidates (KPNA2, DTL, BACE2, DTYMK, E2F3 and SLC25A13) that showed excellent diagnostic accuracy (AUC >90.0%) in tissue." (PMID 36320118, 2022). "Interestingly, by interrogating TCGA and GTEX data, we found that BACE2 is highly expressed in melanoma patients compared to healthy donors, and its level of expression correlates with poor prognosis." (PMID 32749065, 2020). "A similar behavior was also observed when BACE2 was genetically knocked down excluding off‐target effects of the drug and demonstrating that the impairment of BACE2 expression directly impacts on cell proliferation in metastatic melanoma cells (Fig EV5C)." (PMID 32749065, 2020). "Finally, as mechanotransduction modulates also cancer cell proliferation and we previously observed that BACE2 inhibition affects melanoma cell proliferation, we wondered if amyloids-induced YAP activation might contribute also to tumor proliferation." (PMID 38199984, 2024). "To verify that protein aggregates mediate YAP activation, as previously observed in melanoma, we analyzed the secretome of BXPC3 cells treated with BACE2 inhibitor (3I)." (PMID 38199984, 2024). "Four of those showed reliably quantifiable cfRNA copies in plasma samples and specific expression to melanoma (KPNA2, DTL, BACE2 and DTYMK)." (PMID 36320118, 2022). "To get insights into the mechanism that links BACE2‐dependent protein aggregates and YAP, we supplemented primary melanoma IGR39 cells with metastatic IGR37 conditioned medium and we measured the CTGF expression as exemplary of YAP target genes." (PMID 32749065, 2020). "Hence, metastatic melanoma cells (IGR37 and WM266.4) treated with BACE2 inhibitor showed reduction in migration capacity, which was rescued by the administration of rPMEL amyloid fibrils." (PMID 38199984, 2024). "We identified KPNA2, DTL, BACE2 and DTYMK messenger RNA (mRNA) upregulated in melanoma versus nevi tissues by unsupervised data mining (N = 175 melanoma, N = 20 normal skin, N = 6 benign nevi) and experimentally confirmed differential mRNA expression in vitro (N = 18 melanoma, N = 8 benign nevi)." (PMID 36320118, 2022).
melanoma (continued). "In summary, we have identified KPNA2, DTL, BACE2 and DTYMK cfRNAs as potential pan‐tumour liquid biopsy markers for prognostic and therapy monitoring in melanoma independent of the mutational genotype." (PMID 36320118, 2022). "Through the re‐analysis of single‐cell RNA‐Seq (sc‐RNA‐Seq) data derived from 31 melanoma patients, we found that KPNA2, DTL, BACE2 and DTYMK are not only expressed by melanoma cells, but also by non‐malignant cells such as endothelial cells, cancer‐associated fibroblasts (CAFs), and immune cells." (PMID 36320118, 2022). "Thus, we silenced BACE2 in metastatic IGR37 melanoma cells (iBACE2 KD IGR37), by using a pLKO‐TET‐on BACE2 shRNA (Fig EV4C)." (PMID 32749065, 2020). "Notably, we observed that BACE2 inhibition significantly reduced proliferation in both melanoma and PDAC cells, but the presence of amyloid fibrils did not counteract this inhibitory effect." (PMID 38199984, 2024). "Additionally, BACE2 cleaves the pigment cell–specific melanocyte protein (PMEL) and controls pigmentation in zebrafish and mice and, partly, hair pigmentation in humans as well as PMEL-dependent melanoma metastasis formation." (PMID 38888964, 2024). "Receiver operating characteristic (ROC) curves showed an area under the curve (AUC) >90.0% for KPNA2, DTL, BACE2, DTYMK, E2F3 and SLC25A13, >80.0% for CCNA2, FOXM1, KIF4A, SLC45A2, COPS8, SLC45A13 and 70.0% for CDC25A and LINC00520; all significantly discriminating melanoma from benign nevi." (PMID 36320118, 2022).
ocular melanoma (6 papers, 2021 to 2025). A melanoma that arises from the structures of the eye or ocular adnexa. "Upon further functional analysis, the authors found that the BACE2 mRNA upregulation was associated with intracellular calcium release leading to ocular melanoma progression." (PMID 39518125, 2024). "In ocular melanoma, BACE2 has been found to mediate intracellular calcium release from the endoplasmic reticulum and support tumor progression by regulating the expression of TMEM38B, a cation channel protein in the endoplasmic reticulum membrane." (PMID 39981249, 2025). "METTL3-mediated m6A was involved in the high expression of beta-secretase 2 (BACE2), which had been shown to play an oncogenic role in ocular melanoma." (PMID 36830067, 2023). "Another remark of the connection between BACE2 activity and modulation of intracellular pathways to support cancer growth comes from a study on ocular melanoma." (PMID 33926496, 2021). "Furthermore, recent reports indicate the potential role of BACE2 in ocular melanomas as a therapeutic target." (PMID 36320118, 2022).
type 2 diabetes (6 papers, 2013 to 2024). "BACE2 has also been linked to type 2 diabetes and tumor progression." (PMID 39109301, 2024). "TMEM27 and BACE2 expression might be involved in regulating the β-cell number not only in a disease state like type 2 diabetes but also in other conditions associated with increased insulin demand such as the metabolic syndrome or obesity." (PMID 24905913, 2014). "Another BACE2 target, implicated in type 2 diabetes (T2D), is hIAPP (human Islet Amyloid Polypeptide) an amyloidogenic protein, hallmark of T2D." (PMID 33926496, 2021). "Several studies assess an involvement of BACE2 in type-2 diabetes, where BACE2 inhibition increase β-cell mass favoring glucose homeostasis." (PMID 33926496, 2021). "On the other hand, BACE2 has been targeted only more recently, in particular because it has been found to be involved in type 2 diabetes and upregulated in a broad range of tumors where its activity has been correlated with tumor progression." (PMID 33926496, 2021). "Due to this, selective BACE2 inhibitors developed by researchers primarily concern the treatment of type 2 diabetes mellitus (T2DM) and but not AD." (PMID 35883551, 2022).
breast carcinoma (4 papers, 2020 to 2022). "Prelid1 is a prognostic gene in breast cancer that forms a complex in the mitochondrial intermembrane space to prevent apoptosis, and BACE2 (beta-secretase 2) plays a role in melanosome amyloid formation during melanocyte differentiation." (PMID 32831131, 2020). "The first indication that β-secretases might be involved in cancer came from the observation that BACE2 are highly expressed in breast cancer and colon adenocarcinoma." (PMID 33926496, 2021). "In addition, previous studies have shown that BACE2 is upregulated in primary breast cancer and colorectal cancer as well as in colorectal adenomas, thus indicating the key role for BACE2 in malignant tumour progression." (PMID 31856384, 2020).
Hirschsprung disease (4 papers, 2021 to 2024). Hirschsprung disease (HSCR) is a congenital intestinal motility disorder that is characterized by signs of intestinal obstruction due to the presence of an aganglionic segment of variable extent in the terminal part of the colon. "For example, DSCAM cooperates with COL6A2 in congenital heart defects and may interact with BACE2 to increase susceptibility to Hirschsprung disease." (PMID 37712356, 2023). "Previously, we identified several BACE2 rare variants in Hirschsprung disease (HSCR) patients and proved that BACE2-mediated APP cleavage might represent a novel HSCR pathogenesis mechanism in enteric nervous system." (PMID 35110536, 2022).
amyloid (3 papers, 2016 to 2024). "Eliminating the third BACE2 copy in T21 resulted in AmyloGlo+ deposits with neuritic plaques and neuron loss, while the trisomic BACE2 level protected against early amyloid plaque pathology, suggesting BACE2 as a therapeutic target to delay AD onset." (PMID 39062993, 2024). "The capacity of BACE2 to cleave super-optimal concentrations of hIAPP in vitro and modulate fibrillogenesis suggests a potential new therapeutic approach to overcoming amyloidosis associated with T2D." (PMID 26840340, 2016). "Furthermore, we directly demonstrated that the trisomic level of BACE2 protected T21-hiPSC organoids from early AD-like amyloid plaque pathology, therefore proving the physiological role of BACE2 as an AD-suppressor gene." (PMID 32647257, 2021). "Based on our findings that BACE2 proteolytically cleaves hIAPP at residues F15 and F23, one may predict BACE2 therapy as means for disrupting both IAPP-IAPP and IAPP-Aβ interactions at a molecular level and, in so doing impede homo- and hetero-amyloidosis." (PMID 26840340, 2016). "Due to the lack of amyloidosis in rodents, the possible effect of a BACE2 inhibitor on IAPP would be undetectable in this model." (PMID 26840340, 2016).
glioblastoma (3 papers, 2020 to 2024). The most malignant astrocytic tumor (WHO grade IV). "Interestingly, in glioblastoma, patients with higher BACE2 expression exhibited an unfavorable outcome." (PMID 33653351, 2021).
pancreatic cancer (3 papers, 2012 to 2024). "The relative contribution of BACE1 and BACE2 to the overall activity of β-secretase in pancreatic cancer cell lines and tissues remains an area of active research." (PMID 22797723, 2012). "Ultimately, increased understanding of BACE1 and BACE2 expression and activity in pancreatic cancer will allow optimal selection of β-secretase inhibitors that have greater efficacy in reducing the viability of pancreatic cancer cells." (PMID 22797723, 2012). "The commercially available Calbiochem β-secretase inhibitor has 15 times greater ability to inhibit BACE1 compared to BACE2 (according to the manufacturer) and it required prolonged time in culture to inhibit pancreatic cancer cell survival." (PMID 22797723, 2012). "Both BACE proteins have been reported in pancreatic tissue, but reports differ on BACE1 and BACE2 expression and activity in pancreatic ductal and acinar cells, which are cell types proposed to give rise to pancreatic cancer." (PMID 22797723, 2012). "The strongest positive contributions, however, do not come from a set of genes with as coherent a functional annotation as the negatives except with regard to insulin trafficking and secretion; BACE2 and PIM-3, which is also known to promote human pancreatic cancer growth." (PMID 26039411, 2015).
preeclampsia (3 papers, 2020 to 2024). Preeclampsia is a hypertensive disorder of pregnancy that is characterized by new-onset hypertension with proteinuria presenting after 20 weeks of gestation, and depending on mild or severe forms may initially present with severe headache, visual disturbances, and hyperreflexia. "Applications include the use of sVEGFR3 as a BACE2 marker in conditions characterized by altered sVEGFR3 levels, e.g., preeclampsia, hypertension in systemic sclerosis, or treatment-induced changes in sVEGFR3 in VEGFR3-dependent diseases, such as sunitinib-treated cancers." (PMID 38888964, 2024).
dyslipidemia (2 papers, 2014 to 2026). "BACE2 levels correlated positively with insulin resistance and dyslipidemia, with HbA1c emerging as the strongest determinant." (PMID 42221820, 2026).
Hypertension (2 papers, 2024). The presence of chronic increased pressure in the systemic arterial system. "Consistent inheritance of variants within populations has also been documented in academic research on maize (ZmBAM1d), Astyanax mexicanus, Ailuropoda melanoleuca (Bace2), great apes (acan), and human diseases such as hypertension (ace)." (PMID 39028586, 2024).
Insulin resistance (2 papers, 2021 to 2026). Increased resistance towards insulin, that is, diminished effectiveness of insulin in reducing blood glucose levels. "Collectively, these results reveal that BACE2 suppression in an obesogenic setting leads to exacerbated body weight gain, hyperinsulinemia, and insulin resistance." (PMID 34015524, 2021). "In summary, the present study shows that BACE2 inhibition in mice under a HFD feeding exacerbates body weight gain, hyperphagia, hyperinsulinemia, and insulin resistance." (PMID 34015524, 2021).
metastatic melanoma (2 papers, 2020 to 2024). A melanoma that has spread from its primary site to another anatomic site. "Knowing that BACE1 and BACE2 are both involved in amyloid processing, we hypothesized that BACE2 should be mainly responsible for amyloid maturation in metastatic melanoma as it is more expressed in metastatic compared to primitive cells, while BACE1 shows an opposite behavior (Fig EV4B)." (PMID 32749065, 2020). "Therefore, we can conclude that BACE2 KD effectively diminishes PMEL amyloid‐like structures in the extracellular space and leads to YAP inactivation in metastatic melanoma cells." (PMID 32749065, 2020).
Obesity (2 papers, 2014 to 2021). Accumulation of substantial excess body fat. "Thus, we conclude that inhibition of BACE2 may aggravate the adverse metabolic effects associated with obesity." (PMID 34015524, 2021). "This prompted us to explore the impact of BACE2 suppression on the regulation of glucose and energy homeostasis in a model of diet-induced obesity." (PMID 34015524, 2021). "Here, we aimed to investigate the effects of BACE2 suppression on glucose homeostasis in a model of diet-induced obesity." (PMID 34015524, 2021).
osteosarcoma (2 papers, 2021). A usually aggressive malignant bone-forming mesenchymal neoplasm, predominantly affecting adolescents and young adults. "Hence, I have compared the prognostic gene set for osteosarcoma, Cox univariate and multivariate analysis showed that BACE2, ING2 ALOX5AP, HLA-DMB, HLA-DRA, and SPINT2 were not the independent prognostic factors for osteosarcoma." (PMID 33520450, 2021).
viral infection (2 papers, 2021 to 2022). "The capacity of virus infection was further confirmed with SARS-CoV-2 wild virus to infect HeLa cells stably expressing bACE2-Rm." (PMID 33335073, 2021). "Although varied SARS-CoV-2–related coronaviruses have been isolated from bats and SARS-CoV-2 may infect bat, the structural basis for SARS-CoV-2 to utilize the human receptor counterpart bat angiotensin-converting enzyme 2 (bACE2) for virus infection remains less understood." (PMID 33335073, 2021). "We report the binding between intermediate horseshoe bat ACE2 (bACE2-Ra) and SARS-CoV-2 receptor-binding domain (RBD), supporting the pseudotyped SARS-CoV-2 viral infection." (PMID 35874946, 2022).